CES1P1 (carboxylesterase 1 pseudogene 1)
Description:
Has no esterase activity.
Synonyms: PCE-3; CESR; CES1A3; formerly CES4
Gene: Transcribed unprocessed pseudogene on chromosome 16 (55,760,642 to 55,793,960, forward strand). Ensembl gene ENSG00000228695.
Subcellular location: Secreted
Diseases named in the same sentence as CES1P1 in open-access papers:
CES1P1 is named in the same sentence as 4 diseases in open-access papers, as found by Europe PMC text mining. Sharing a sentence is not in itself a finding about the gene and the disease. The quoted sentences say what the papers report.
gastric cancer (1 paper, 2021). A primary or metastatic malignant neoplasm involving the stomach. "CES1P1 are associated with the progression of gastric cancer." (PMID 33765954, 2021).
cancer (1 paper, 2016). A tumor composed of atypical neoplastic, often pleomorphic cells that invade other tissues. "However, a subsequent study of Japanese cancer patients revealed the SNP -816 A>C to reside in CES1P1 and being absent or rare in CES1A2, thus questioning the exact nature of the association with the response to imidapril." (PMID 27662362, 2016).
tumor (1 paper, 2024). "Of note, from RCC42, three deep deletions, UGT2B17, OR4P4 and CES1P1 were consistently observed in both parental tumor and organoid lines." (PMID 38923304, 2024).
CES1P1 also shares sentences with these, for which no sentence is quoted: cervical squamous cell carcinoma (1 paper).